CCND1 (cyclin D1)
Diseases named in the same sentence as CCND1 in open-access papers (continued):
Sharing a sentence is not in itself a finding about the gene and the disease.
tumor (continued). "Submitting our gene list to the MSigDB identified gene sets characteristic of an invasive phenotype in tumours of high FN1/CCND1 expression, including upregulation of gene sets related to extracellular matrix, cell movement, cancer-specific invasion and mesenchymal phenotype." (PMID 32037399, 2020). "Additionally, knockdown of IGF2BP3 also repressed the expression of Cyclin D1, Ki67 (the marker for tumor proliferation), VEGF, and CD31 (the marker for tumor vessels) in vivo." (PMID 32993738, 2020). "Moreover, administration of wogonin and sunitinib also inhibited the expression of CDK4, p-RB, and Cyclin D1 in tumor tissues." (PMID 32792963, 2020). "Moreover, Cyclin D1 has been recognized as an oncogene, and its overexpression can promote the proliferation of tumor cells." (PMID 32256207, 2020). "Subsequently, STAT3 acetylation activates Cyclin D1 promoter and induces the tumor proliferation." (PMID 33382817, 2020). "Tumors of HFD-fed mice increased their expression of proliferation-promoting cyclin D1, β-catenin, Src phosphorylation, Akt phosphorylation, and Smad phosphorylation when compared with tumors in ND-fed mice, with the changes in tumor-bearing HFD-fed mice being reversed by aspirin." (PMID 32121098, 2020). "In our study, the mRNA and protein levels of cyclin D1 were high in the xenograft tumours." (PMID 32382281, 2020). "More interestingly, CCND1 expression in CTCs was significantly decreased in patients with disease control after four infusions of nivolumab, suggesting that tumor-specific T cells may lyse tumor cells expressing CCND1." (PMID 33299117, 2020). "miR-15a and miR-16 which act as tumor suppressors by targeting CCND1, WNT3A and Bcl2 may be considered to have therapeutic potential in NEPC by either acting independently or being used as a combinational therapy with chemotherapy." (PMID 33426506, 2020). "Similarly, we found that tumor tissue had a lower expression level of cytoplasmic CCND1 than adjacent normal tissue, and tumors with higher cytoplasmic CCND1 had lower Gleason score (P = 0.028)." (PMID 32566661, 2020). "Results from both in vitro and in vivo studies could be summarized to state that DZG downregulated cyclin D1 expression, leading to the induction of the cell cycle arrest in the G1 phase, leading to a reduction in the tumor volume." (PMID 32545675, 2020). "STAT5 could also induce chromatin structure remodelling and the overexpression of cyclin D1 to enhance tumour formation." (PMID 32872372, 2020). "In collaboration with cyclin-dependent kinases (CDK) 4 and 6, Cyclin D1 stimulates progression through the G1 phase of the cell cycle via retinoblastoma protein inactivation, which may lead to tumor formation." (PMID 31673890, 2020). "Further studies revealed that these miRNAs function as tumor suppressors to induce apoptosis by repressing the B-cell lymphoma 2 (Bcl-2) gene, and inhibit the cell cycle by the repression of cyclin-related genes such as CCND1 and CCNE1." (PMID 32660045, 2020). "In vitro study showed that AIF1 promoted tumor growth via the NF-κB/cyclin D1 pathway." (PMID 33186124, 2020). "A study indicated that miR-195 expression could act as a tumor metastasis suppressor via attenuating CCND1." (PMID 32565738, 2020). "Moreover, we detected 15 gene amplifications in six different tumor specimens, including AR, CCND1 (n = 2), FGF19 (n = 2), FGF3 (n =2), KRAS (n = 2), MYC (n = 2), CCND3, CCNE1, CDK6, and RICTOR." (PMID 33203166, 2020). "Importantly, high circ‐CCND1 was positively correlated with larger tumour size (P < .001), poor differentiation (P = .007) and advanced TNM stage (P = .004; Table." (PMID 31951319, 2020).
tumor (continued). "Notably, a prior study on the efficacy of the O-methylated flavone wogonin on HCC, indicated accelerated phosphorylation of cyclin D1 (CCND1) to be a factor in the suppression of tumor growth." (PMID 33292207, 2020). "c-Myc and Cyclin D1 are both important regulators for tumor growth." (PMID 32774415, 2020). "In view of clinical analyses showing a correlation between total cyclin D1 expression and tumor invasiveness and metastasis, our studies suggest further studies assessing membrane-associated cyclin D1 may be warranted." (PMID 32948740, 2020). "Therefore, evaluating the expression of key cell proliferation markers such as the cell-cycle-regulated gene, cyclin-D1, the nuclear protein, Ki67, and Pcna is beneficial to understand the mechanism behind tumor growth suppression." (PMID 33233444, 2020). "Moreover, LD plot showed strong LD between exonic RB1 SNP (rs121913300) and intergenic CCND1 SNP (rs614367) in tumor patients." (PMID 32373934, 2020). "Patient #9 also had a CCND1 copy number gain in the HER2‐negative tumour component." (PMID 32058674, 2020). "We aimed to explore the function of CCND1 in tumor progression in LSCC." (PMID 32380883, 2020). "Indeed, our work demonstrated that miR-302a was a potent tumor suppressor in EC, the effect of which was mediated in part by regulation of cyclin D1." (PMID 31001342, 2019). "It has been shown that one of the downstream effector of NF-κB is Cyclin-D1 and antitumor components such as curcumin could down-regulate cyclin-D1 due to NF-κB inhibition in tumor cells." (PMID 32184861, 2019). "A series of rescue experiments was conducted to test whether CCND1 mediates the tumor-suppressive actions of miR-625 overexpression in ccRCC cells." (PMID 31434797, 2019). "Moreover, ectopic expression of DACH1 significantly inhibited the expression of CXCL1, Ki67, and cyclin D1 in tumor tissues compared with A549 cells with empty vector." (PMID 31998654, 2019). "Besides, by interacting with PI3K-AKT-mTOR, NF-κB controls tumor proliferation through the regulation of c-myc and cyclin D1." (PMID 31396300, 2019). "Importantly, RN181 expression is inversely correlated with the expression of cyclin D1 and CDK4 in GC clinical samples, substantiating the role of the RN181–cyclin D1/CDK4 pathway in control of the tumour growth of GC." (PMID 30714150, 2019). "In this regard, previous studies have shown that SGKs might modulate tumor growth via regulating cyclin D1 expression, GSK3-β/β-catenin cascade as well as epithelial-mesenchymal transition (EMT) in HCC cells." (PMID 30975125, 2019). "In addition, fucoxanthin down-regulated tumor Cyclin D1 expression by 0.7-fold of that observed in the tumors of the control mice." (PMID 30705512, 2019). "In contrast, our findings show that copanlisib suppresses tumor growth in HCC cells mainly by triggering a G1 cell cycle arrest by inhibiting the cyclin D1/CDK4/CDK6 axis, without causing apoptosis." (PMID 30962952, 2019). "Hence, we checked the molecular interaction between tumor-associated proteins such as AKT, PI3K, mTOR, and cell cycle regulating proteins such as CHK1, CHK2, CDK6, Cyclin D1, and proteins from MAPK signaling including MEK1, p38MAPK, and SAPK/JNK." (PMID 31783627, 2019). "Our results indicated that the level of CCND1 and tumor grade may be related to tumor recurrence in ccRCC patients." (PMID 31183974, 2019).
tumor (continued). "Additionally, the region harboring the cyclin D1 (CCND1) oncogene was amplified and the region harboring the tumor suppressor genes, Cyclin Dependent Kinase Inhibitor 2A (CDKN2A) and CDKN2B, was deleted in both pre- and post-CCRT samples." (PMID 31097034, 2019). "Finally, restoration of CCND1 expression attenuated the tumor-suppressive effects of miR-625 overexpression on the malignant phenotype of ccRCC cells." (PMID 31434797, 2019). "Importantly, in clinical tumour samples, RN181 was reversely correlated with the expression of cyclin D1 and CDK4, highlighting the role of the RN181–cyclin D1/CDK4 pathway in the control of tumour growth." (PMID 30714150, 2019). "(B) Liver tumor lysates were immunoblotted for Cyclin d1, cMyc, and P-cJun." (PMID 30990169, 2019). "Of note, 4βHWE treatment suppressed the expression of the c-Myc, Axin2, cyclin D1, and survivin Wnt target genes in the tumor tissues, as well as the induction of Ser33/Ser37/Thr41 phosphorylation of β-catenin, indicating that 4βHWE inhibits Wnt signaling in vivo to attenuate tumor proliferation." (PMID 30909473, 2019). "Indeed, this was the orientation bias observed for integrations into both Ccnd1 and Rasgrp1 in TP-16 tumor DNA." (PMID 31815961, 2019). "Also, CCND1 is amplified in 5–20% of HBCs and this occurs preferentially in ER positive tumours, being its prognostic significance proposed by different authors." (PMID 31461477, 2019). "In multivariable analysis, patients with ER+/LN+/HER2− CCND1-amplified tumours were found to have worse 15-year BCSS (HR = 2.07, 95% CI, 1.12–3.83), and comparable trends were noted in luminal A (HR = 1.97, 95% CI, 0.95–4.08) and luminal B (HR = 2.01, 95% CI, 0.94–4.30) subgroups." (PMID 30819233, 2019). "Therefore, we analyzed the expression of cyclin D1 and other relevant cell cycle regulators in multiple patient tumor collections to evaluate the potential clinical implications of our findings." (PMID 30718512, 2019). "Treatment of tumor cells with ginger extract resulted in apoptosis and decreased expression of the prosurvival genes, NFκB, Bcl-X, Mcl-1 and Survivin, as well as the cell cycle regulating proteins, cyclin D1 and CDK4." (PMID 31394732, 2019). "In addition, an in vitro study showed that upregulating MIR193A decreased tumor cell proliferation and migration, at least partly, by directly targeting cyclin D1 (CCND1) and ETS proto-oncogene 1 (ETS1) expression." (PMID 31523496, 2019). "Moreover, luminal A CCND1-amplified tumours display gene expression changes consistent with a more aggressive phenotype." (PMID 30819233, 2019). "In total, 56% patients with CCND1 high expression contained low‐grade tumor group, but only 36% patients with CCND1 low expression contained low‐grade tumor (chi‐square test, P < 0.001), indicating CCND1 mRNA level decreases with increasing ccRCC tumor grades (P < 0.001)." (PMID 31183974, 2019). "Furthermore, the expression levels of downstream genes regulated by NF-κB such as Survivin, Bcl-2, VEGF, and cyclin D1, were also determined, which were found to be involved in tumor survival and chemoresistance, angiogenesis, and proliferation, respectively." (PMID 31729451, 2019). "Finally, we further characterised luminal A CCND1-amplified tumours by determining if any shared genes exist between amplified tumours in luminal A vs. luminal B molecular subgroups." (PMID 30819233, 2019). "Moreover, Sal-B or cisplatin treatment significantly decreased tumor tissue level of cyclin D1 in ESC injected mice which is required for the progression through the G1 phase of the cell cycle to induce cell migration and angiogenesis." (PMID 31726654, 2019).
tumor (continued). "Moreover, knockdown of MIR4435-2HG increased E-cadherin and decreased N-cadherin, vimentin, c-Myc, β-catenin, cyclin D1 and survivin expression in tumor xenografts." (PMID 31484163, 2019). "The changes of tumor volume, body weight, NF‐κB activation, MAPK activation, and tumor progression‐associated proteins (MMP‐9, XIAP, VEGF, and Cyclin‐D1) after regorafenib treatment were evaluated with digital caliper, digital weight, and ex vivo Western blotting assay." (PMID 30801954, 2019). "ASK1, which was known to participate in colon and skin tumourigenesis, could increase the expression of cyclin D1 through AP‐1 activation and cyclin D1 could up‐regulate ASK1 via the Rb‐E2F pathway in GC to stimulate tumour growth." (PMID 30714150, 2019). "Our study further confirmed that gramicidin regulated cyclin D1 expression with G2/M inhibition and apoptosis, implying that modulating cyclin D1 might serve as a potential anti-tumor target." (PMID 31767027, 2019). "Moreover, Fx down-regulated protein expression of an essential regulator for the cell cycle, Cyclin D1, in the xenografted tumor tissues." (PMID 30705512, 2019). "The animal study for oral squamous carcinoma also revealed tumor stasis and cell cycle arrest in G0/G1 phase, associating with activation of AMP kinase pathway to decrease cyclin D1, cyclin-dependent kinase 4/6 (CDK4/6) and phosphorylated retinoblastoma protein." (PMID 31470817, 2019). "CCND1 (cyclin D1): In contrast to its underexpression identified by the conventional analyses, it has been frequently reported as overexpressed in intestinal metaplasia, human neoplasias, and several tumors." (PMID 31616468, 2019). "In order to understand why CCND1 amplification confers a worse survival in luminal A tumours, we first examined the expression of genes related to the cell cycle and cell proliferation across all tumours of cohort 1 within the context of the PAM50 subtypes." (PMID 30819233, 2019). "Having discovered that GR liganding suppresses mutant HA-Y537S ER chromatin association with the CCND1 enhancer, we next wished to determine whether SGRM treatment could also reduce mutant Y537S ER tumor growth in vivo." (PMID 31340854, 2019). "Therefore, we propose that the FOXO3/CCND1 axis plays an essential role in LINC01355-mediated tumor suppression." (PMID 31243265, 2019). "Therefore, nomograms for the prediction of recurrence probabilities, which included CCND1 and tumor grade, were constructed." (PMID 31183974, 2019). "In fact, the association of high mutational burden and CIN with short PFS remained as a trend in multivariable Cox models that combined mutational burden, CIN, co-occurring CCND1 and CDKN2A mutations, tumor site, and HPV status (with p = 0.079 and p = 0.059, respectively)." (PMID 30934880, 2019). "Besides, median pre-treatment rate of positive tumor cells for c-myc, Cyclin D1, and Zeb-1 were 30% (range 10–60%), 50% (15–60%), and 12% (5–25%), respectively." (PMID 31390375, 2019). "Then, the in vivo experiment also confirmed that Mfn2 could inhibit the tumor growth, and depress the Cyclin D1, Ras, Myc, NF-κB p65, Erk1/2 and mTOR protein expression." (PMID 31384172, 2019). "Most notably, patients with ER-positive CCND1-amplified tumours also show reduced survival times." (PMID 30819233, 2019). "The mRNA and protein levels of CCND1 were significantly enhanced in ccRCC tumor tissues." (PMID 31183974, 2019). "Moreover, curcumin inhibits the proliferation of various tumor cell lines, and in most cells, this inhibition is related to the down-regulation of the expression of cyclin D1 protein." (PMID 31998463, 2019). "In addition to the tumor progression, CCND1 cyclin, cyclin-dependent kinases and cyclin-dependent kinase inhibitors are well-known regulators of cell cycle transition in CRC." (PMID 31718693, 2019).
tumor (continued). "Second, luminal A CCND1-amplified tumours display gene expression changes consistent with more aggressive tumours, specifically increased MKI67 and decreased PGR gene expression in addition to an overlap in genes differentially expressed in CCND1-amplified luminal B tumours." (PMID 30819233, 2019). "It was concluded that tumor expression of cyclin D1 may serve as a predictive biomarker in selecting patients with HNSCC, who may benefit from naCHT." (PMID 29332262, 2018). "In the present study, we demonstrated that LN229 cells, a GBM cell line, expressed mGluR4, and pharmacological activation of the receptor inhibited proliferation of the tumor cells, indicated by cell viability reduction, cell cycle arrest and downregulation of cyclin D1 expression." (PMID 29867331, 2018). "Cyclin D1 promotes cell cycle progression and tumor cell growth." (PMID 29987260, 2018). "Also in tumor tissues, we found that high levels of Vav1 and low levels of p‐Akt correlated with low Cyclin D1 staining, suggestive of the inverse relationship between Vav1 and activated Akt1." (PMID 29658179, 2018). "miR-889, Cyclin D1, Annexin A2) and less tumor-suppressive RNA (ex." (PMID 30546829, 2018). "Furthermore, immunohistofluorescence staining of the excised tumour tissue visually revealed that β-catenin and Cyclin D1 were decreased in the PF treatment groups." (PMID 29789528, 2018). "To assess, if the expression of the miR-449a target CCND1 may also correlate with tumour grade and type, we retrieved expression data from TCGA." (PMID 29720725, 2018). "The nuclear β-catenin associated with the T cell factor (TCF)/ lymphoid enhancer factor (LEF) family of transcription factors plays roles in several compounds including cyclin D1 and c-myc, which could act as a tumour activator in colorectal cancer." (PMID 29463902, 2018). "For instance, CCND1 can promote cell proliferation, leading to transition tumor progression." (PMID 29342086, 2018). "It was selected for subsequent analysis as a tumour suppressive role of miR-449a has been suggested in a number of malignancies, most notably in prostate cancer by targeting classical proto-oncogenes CCND1, c-Myc and HDAC-1." (PMID 29720725, 2018). "Thus, activation of c-Rel appears to induce expression of cyclin D1, c-Myc, and Bcl-xL that promote tumor growth." (PMID 30250646, 2018). "Additionally, cyclin D1 was highly overexpressed in primary site tumor (87.9%) and local recurrent (93.3%) samples." (PMID 30236142, 2018). "Interestingly, in agreement with in vitro observations, tumor sections in the treatment group showed a significant reduction in the cyclin D1 and Ki-67 staining." (PMID 30149527, 2018). "Indeed, FISH analysis failed to produce a detectable result in limited fractions of tumor tissues for each gene (ranging from 6 tissue samples for cKIT to 12 for CCND1)." (PMID 29492214, 2018). "Finally, to investigate EGFR and Src transcription in the tumor, mRNA extracted from the tumor tissue was used to determine the expression of the c-Myc and cyclin D1 by quantitative reverse transcription-polymerase chain reaction (qRT-PCR)." (PMID 29641465, 2018). "Moreover, ZEB1 expression was positively correlated with expression of B-cell lymphoma-extra large (Bcl-xL) and cyclin D1, which are key components of tumor chemoresistant mechanisms." (PMID 29352223, 2018).